IL1B (interleukin 1 beta)
Diseases named in the same sentence as IL1B in open-access papers (continued):
Sharing a sentence is not in itself a finding about the gene and the disease.
periodontitis (continued). "Nicotine absorbed by oral mucosa displays stimulatory action on periodontitis-induced osteoclastic bone resorption, which is mediated by increased IL-1β in the periodontal niche." (PMID 36359775, 2022). "It was observed that salivary IL-1β levels increased and periodontal parameters worsened with increased stages of periodontitis." (PMID 35270581, 2022). "The IL-1B+3953 C/T genotype was significantly more predominant in periodontitis patients than in controls, whereas C/C genotype prevalence was significantly lower in the test group." (PMID 36429405, 2022). "LPS lead to the dysregulation of host immuno-inflammatory response and the release of a large number of inflammatory factors, such as TNF-α and IL-1β, which eventually result in periodontitis." (PMID 35464198, 2022). "Systemic inflammation, indicated by elevated levels of TNFα, IL-1β, IL-6, and IFNγ in the serum, is clinically present in patients with periodontitis." (PMID 35874771, 2022). "Clinically high levels of IL-1β correlate to the severity of periodontitis and P. gingivalis counts; periodontitis is characterized by an increase of the M1/M2 ratio." (PMID 36551420, 2022). "Because there is strong evidence of the role of IL-1β in the physiopathology of periodontitis, recent research has tried to discover its link to peri-implantitis." (PMID 35061134, 2022). "Immunostaining images showed a stronger signalling intensity for NLRP3, cleaved CAS1, and IL-1β in the connective tissue of periodontitis compared to a healthy gingiva." (PMID 35563469, 2022). "Concurrent presence of all red complex periodontal pathogens in IL-1B (3954)-SNP positive periodontitis patients was identified." (PMID 35122548, 2022). "The frequency of the IL-1B+3953 C/C genotype was significantly decreased in the group with periodontitis." (PMID 36429405, 2022). "IL-1β levels in gingival crevicular fluid (GCF) of individuals with periodontitis were significantly higher than those in healthy individuals in previous studies." (PMID 35270581, 2022). "Discussion: The findings provide upregulated SLC2A3, FPR2, TREM1, and IL1B in neutrophils as a future research direction on the mode and mechanism of cell death in periodontitis and their role in disease pathogenicity." (PMID 36686646, 2022). "In the process of periodontitis, IL-1β promotes fibroblasts to secrete collagenase, interstitial lytic enzyme, and gelatin-degrading enzyme, which leads to matrix degradation, loss of connective tissue, and destruction of periodontal tissue." (PMID 36430410, 2022). "This is in keeping with prior research, which found that LPS-stimulated periodontitis cells, microglia cells and an IL-1β-stimulated ATDC5 chondroprogenitor cell line dramatically enhance METTL3 expression and m6A levels." (PMID 36555481, 2022). "In parallel, we detected elevated levels of TRAP+ osteoclasts, TNF-α and IL-1β in mice receiving a periodontitis patient donated microbiome." (PMID 35958276, 2022). "Salivary levels of miR-1246 in patients with chronic periodontitis were positively correlated with the levels of IL-1β, IL-6, IL-17, TNF-α, MMP-1, MMP-8, TIMP-1, PLI, GI, PD, and AL (P < 0.05)." (PMID 35942384, 2022). "IL-1β was markedly increased in the saliva of patients with periodontitis and gingivitis, as compared to that of healthy individuals." (PMID 36093182, 2022). "IL-1α, IL-1β and IL-6 are proinflammatory cytokines that are thought to play a role in periodontitis development." (PMID 35571048, 2022). "Accordingly, the present study was designed to evaluate how effective the consumption of green tea can be in terms of reducing the IL-1β concentration level in the saliva of patients with chronic periodontitis." (PMID 35706460, 2022). "In line with this, IL-1β was also proved to promote inflammatory cell infiltration toward alveolar bone in experimental periodontitis, thus further aggravating alveolar bone loss." (PMID 36093182, 2022).
periodontitis (continued). "The study findings revealed that participants with severe periodontitis had increased concentrations of IL-1β and MMP-8, while smokers also had slightly reduced concentrations of IL–8 and MMP-8." (PMID 35626325, 2022). "Collectively, either inhibiting the activation of caspase-4 or blocking the function of IL-1β can attenuate periodontitis-mediated tissue damage, which indicates the critical role of caspase-4-mediated non-canonical pyroptosis in rat periodontitis." (PMID 33869229, 2021). "We found that nicotine significantly enhanced the autophagy of hPDLCs and secretion of IL-1β and IL-8 through α7 nAChR thus aggravating the inflammatory response of the periodontal tissues and periodontitis." (PMID 34732192, 2021). "Our data show that IL-1β, individually, revealed an AUC value of 0.88 for discriminating periodontitis subjects from healthy subjects." (PMID 34001101, 2021). "During 3 weeks of EG, IL-1β expression catches up with IL-1α and continues to increase in periodontitis." (PMID 34072136, 2021). "The positive area of IL‐1β in the second molar root furcation was decreased in ligature‐induced periodontitis mice receiving MCC950 compared with that receiving vehicle." (PMID 33382502, 2021). "IL-1β is a major pro-inflammatory cytokine in periodontitis, and its levels in gingival tissue are related to disease severity." (PMID 34630089, 2021). "Consistently, the active form of IL-1β was highly expressed in periodontal tissues and GCFs from periodontitis patients." (PMID 33869229, 2021). "Similar to human periodontal tissues, Gsdmd cleavage, mature IL-1β release and caspase-4 activation were both significantly increased in ligature-induced rat periodontitis." (PMID 33869229, 2021). "IL-1β, IL-6, and TNF-α are the main inflammatory cytokines of periodontitis, which contribute to inflammation and bone loss during periodontitis." (PMID 34592963, 2021). "Clinical evidence suggested that the gingival crevicular levels of IL-1β and TNF-α are positively associated with the onset and progression of periodontitis." (PMID 33485352, 2021). "Our study showed that the level of IL-1β in PISF among patients with healthy implants was significantly lower than in GCF in patients with all stages of periodontitis." (PMID 33726736, 2021). "Tissue destruction in periodontitis is associated with the positive regulation of inflammasome-associated receptors such as NRLP3 and production of IL-1β." (PMID 34630089, 2021). "NLRP3 inflammasome activation was detected in P. gingivalis-induced periodontitis, leading to upregulation of IL-1β and IL-18 and enhancement of bone resorption." (PMID 34177950, 2021). "The classical proinflammatory cytokine, IL1B, is elevated in periodontitis and can induce resorption of alveolar bone." (PMID 33869630, 2021). "Periodontitis is a chronic inflammatory disease caused by dysbiosis of the oral microbiome and exacerbation of pro-inflammatory cytokines, including interleukin (IL)- 1-beta (IL-1β) and IL-6, and nitric oxide (NO) production, which might lead to tissue destruction." (PMID 34635094, 2021). "Periodontitis is a chronic inflammatory disease that is characterized by elevated production of several pro-inflammatory cytokines, including IL-1β, IL-6, and TNFα, in the oral cavity, which can further contribute to low-grade systemic inflammation." (PMID 33562334, 2021). "IL-1β was regarded as an important marker in various inflammatory diseases, such as inflammatory bowel diseases, neuroinflammatory diseases, periodontitis, etc.." (PMID 34513725, 2021). "We found that the expression level of IL‐1β was increased in periodontitis group compared with that in control group." (PMID 33382502, 2021). "lactis led to reduced plaque and gingival indexes and decreased IL-1β levels in gingival crevicular fluid and was successfully used as an adjunct to the mechanical treatment of periodontitis." (PMID 34630089, 2021).
periodontitis (continued). "It has been found that the mRNA expression of NLR family pyrin domain-containing 3 (NLRP3) and IL-1β is increased in patients with periodontitis." (PMID 34356813, 2021). "Macrophage infiltration, levels of inflammatory cytokines such as IL-6, IL-1β, and TNFα, and M1 macrophage polarization were enhanced in anti-Act1 periodontitis mice compared to wildtype periodontitis mice." (PMID 33748112, 2021). "It had been reported that the level of IL-1β in gingival crevicular fluid is increased at sites affected by gingivitis and periodontitis." (PMID 34299815, 2021). "The application of IL-1ra (a natural inhibitor of IL-1β) suggests the possible function of IL-1ra in controlling periodontal inflammation in an experimental periodontitis model." (PMID 35046930, 2021). "In the following study, we found that the mean level of IL-1β was the highest in patients with severe periodontitis." (PMID 33726736, 2021). "In this study, we provided a statistical correlation between IL-1β levels and the severity of periodontitis, which was consistent with previous reports that IL-1β in saliva or gingival crevicular fluid is a potential biomarker for periodontal disease." (PMID 33869229, 2021). "Several studies have revealed that compared with systemically healthy subjects with periodontitis, T2DM patients combined with periodontitis had a higher level of IL-1β in GCF, while other cytokines were similar between them." (PMID 33417619, 2021). "After the periodontitis model establishment for 1 week, significantly increased mRNA expression of IL-1β, TNF-α, and IL-6 was observed in the IL-17 and IFN-γ groups than in the NS group (p < 0.05)." (PMID 34395635, 2021). "We have earlier shown that these patients with periodontitis had higher salivary levels of interleukin 6 (IL-6) and IL-1β, and elevated pro-inflammatory: anti-inflammatory ratio compared to H." (PMID 35048045, 2021). "As expected, we found that the mean concentration of IL-1β was the highest in patients with severe periodontitis (61.04 ± 41.41 pg/mL)." (PMID 33726736, 2021). "Tumor necrosis factor (TNF)-α and interleukin-1β (IL-1β) are inflammatory cytokines involved in periodontitis, and they can affect and amplify the inflammatory response, resulting in tissue destruction and bone loss." (PMID 34399747, 2021). "IL-1β had previously been shown to be an important proinflammatory cytokine that drove the pathogenesis of periodontitis and often amplified the effect of other cytokines." (PMID 33869229, 2021). "In periodontitis, proinflammatory cytokines, such as IL-1β, IL-6, IL-8, and TNF-α, seem to be the major mediators, involved in the destruction of periodontal tissue." (PMID 34035660, 2021). "These molecules provide potential targets to control IL-1β-related periodontitis in P. nigrescens-infected patients." (PMID 33390812, 2021). "The initiation of PDLSC pyroptosis disrupts the homeostatic balance of bone formation and resorption by releasing IL-1β, consequently aggravating the occurrence of periodontitis." (PMID 33869229, 2021). "IL-1β plays an important role in the pathogenesis of periodontitis also by regulation of the IL-6 production in a variety of cell types, including fibroblasts and epithelial cells." (PMID 33467650, 2021). "This study showed that pro-inflammatory cytokine IL-1β levels are inversely correlated with the recovery rate of periodontitis clinical parameters in hypertensive patients." (PMID 34299815, 2021). "With the expectation of IL-1β level in chronic periodontitis, the results showed significant reductions in the levels of pro-inflammatory cytokines in two subgroups within periodontitis patients." (PMID 34645448, 2021). "Based on their expression, we identified novel epithelial-mesenchymal interactions in periodontitis: the interactions between epithelial IL1B and TNF and stromal target genes." (PMID 33393902, 2021).
periodontitis (continued). "In that study, IL-1β, MMP-8, and Pg were calculated together to obtain a cumulative risk score that was highly correlated with advanced periodontitis." (PMID 34001101, 2021). "The periodontitis group showed significantly higher levels of IL-1β, MMP-8, ICTP, and Pg compared to the healthy group and higher levels of IL-1β, ICTP, and Pg compared to the gingivitis group." (PMID 34001101, 2021). "In this study, combining human periodontitis specimens (n = 87), we found that PDLSCs underwent GSDMD-mediated pyroptosis with typical cell swelling and IL-1β release during periodontitis." (PMID 33869229, 2021). "Periodontitis is characterized by an elevated pro-inflammatory: anti-inflammatory ratio, with increased levels of cytokines such as IL-1β, IL-6 and TNF-α." (PMID 34630089, 2021). "The authors found that the level of IL-1β in GCF increases with the progression of the periodontitis, and in patients with the most severe form of the disease, it is almost 8 times higher than in the control group." (PMID 33726736, 2021). "All of these results support our inclusion of IL-1β as a predictive overall indicator of gingivitis and periodontitis." (PMID 34001101, 2021). "The microbial-immunological axis between periodontitis and IBD was also explored: elevated IL-1β secretion is associated with both IBD and periodontitis." (PMID 34950607, 2021). "Its expression is closely correlated with proinflammatory cytokines production (TNF-α and IL-1β) and with clinical conditions of periodontitis." (PMID 34566966, 2021). "Macrophage polarization toward a higher M1/M2 ratio was shown to be involved in the progression of gingivitis to periodontitis, with sustained IL-1β, IL-6, and TNF-α and diminished IL-10 expression." (PMID 34063147, 2021). "IL-1β is not only related to smoking-related periodontitis, but increasing IL-1β can trigger a series of inflammatory reactions and promote bone resorption." (PMID 34732192, 2021). "IL-1β (+3954), on the other hand, is a pro-inflammatory cytokine that plays a vital role in immune control, inflammation, and bone resorption in periodontitis." (PMID 34501201, 2021). "TNF-α, IL-1β, and IL-6 are the most important inflammation markers of periodontal disease, and its increase has been very well explained in periodontitis as a response to infection with the periodontal pathogens (Porphyromonas gingivalis, etc.)." (PMID 33746772, 2021). "It has been reported that several pro-inflammatory cytokines, including IL-1, -6, and -8, upregulate the secretion of MMP-3, which increased with the progression of periodontitis and was involved in the regulation of IL-1β expression in gingival tissues." (PMID 34209432, 2021). "Both SM and CHX appeared to reduce secretion of the potent pro‐inflammatory cytokine IL‐1β, a marker of active inflammation, IL‐1β's role in bone resorption and tissue destruction in relation to periodontitis has been described." (PMID 33960130, 2021). "The split based on IL-1b separated periodontitis patients with IL-1b levels above a cutoff level of 472 pg/ml." (PMID 33742017, 2021). "Clinically, IL-1β is used as a biomarker to assess the therapeutic outcomes of patients with chronic periodontitis." (PMID 33716675, 2021). "Consistent results also observed in human tissue, a research shows NLRP3 and IL‐1β have been found highly expressed in human gingival tissues with severe chronic periodontitis." (PMID 33382502, 2021). "Patients with periodontitis have substantially higher intensities of IL-1β in salivary and gingival crevicular fluid samples than in healthy controls." (PMID 34501201, 2021). "Both WT-L and AT2-L groups of animals submitted to ligature-induced periodontitis showed a significant increase in IL-1β level when compared to their respective control groups, without ligature, WT-NL and AT2-NL (p < 0.01 and p < 0.05, respectively)." (PMID 34884653, 2021).
periodontitis (continued). "Here, we found that PDLSCs suffered GSDMD-dependent pyroptosis to release interleukin-1β (IL-1β) during human periodontitis." (PMID 33869229, 2021). "The sensitivity and specificity of IL-1β for predicting periodontitis were 88.24% and 62.5%, respectively." (PMID 34199256, 2021). "After periodontal treatment, increased mRNA levels of IL1B in chronic periodontitis were also significantly reduced in peripheral blood mononuclear cells (PBMCs) of patients with BOP ≥ 16% but not of patients with BOP < 16%." (PMID 34177950, 2021). "Human gingiva samples were immunohistochemically characterized for the expression of NLRP3, 8OHdG, cleaved-caspase-1, and IL-1β in periodontitis specimens, compared with that in normal gingival tissues." (PMID 31685946, 2020). "The biological effects of IL-1β depend on its tissue concentration, which is elevated in periodontitis." (PMID 31900383, 2020). "Periodontitis as an inflammatory disease has been known to increase the levels of proinflammatory cytokines, including IL-1α, IL-1β, IL-6, and TNF-α." (PMID 33383828, 2020). "In this study, PGFE inhibited the production of TNF-α, IL-1β, and IL-6, which are the major cytokines involved in periodontitis induced by PG-LPS, as well as the pro-inflammatory mediators NO and PGE2." (PMID 33287198, 2020). "Serum IL-1β levels progressively increased from group to group, from periodontal health to periodontitis, and were significantly different among groups (p=0.000)." (PMID 32997091, 2020). "One study indicated Prevotella induces immune response in periodontitis by regulating IL-1α and IL-1β levels." (PMID 32730353, 2020). "Not only the link between IL-1β and periodontitis was proved by clinical evidence, but also the increased IL-1β triggers a series of inflammatory reactions and promotes bone resorption." (PMID 31900383, 2020). "HGFs were selected for use in the present study because they are the group of cells that are most highly affected by TNF-α and IL-1β in periodontitis." (PMID 32410860, 2020). "Studies showed that higher levels of IL-1β and TNF-α both in gingival crevicular fluid and PICF are associated with periodontitis and peri-implantitis, although there are contradictory results." (PMID 33111201, 2020). "TNF-α and IL-1β are key pro-inflammatory cytokines that are involved in the pathogenesis of periodontitis and decrease wound healing and regeneration." (PMID 32024893, 2020). "In a meta-analysis, it is demonstrated that IL-1α and IL-1β genetic variation are significant contributors to chronic periodontitis." (PMID 32604936, 2020). "Other than the current therapies for IL-1β, are there any potential strategies to target IL-1β in periodontitis?" (PMID 31900383, 2020). "Using a meta-analytical approach, a previous study found that MMP-8, MMP-9, IL-1β, IL-6, and Hb were salivary biomarkers with good capability to detect periodontitis in systemically healthy subjects." (PMID 33383828, 2020). "Biomarkers that decreased after scaling and root planning (SRP) and oral hygiene instruction (OHI) in periodontitis patients were IL-1β, MMP-8, MMP-9, prostaglandin E2 (PGE2), and TIMP-2." (PMID 33383828, 2020). "Salivary evaluations indicate towards an increased level of interleukin (IL)-1β during periodontitis, correlated with the progression of the disease and also indicating its active or inactive status." (PMID 32685098, 2020). "Histopathologic and radiographic evaluation of myoperoxidase, P-selectin, and IL-1β in male rats with induced periodontitis showed that H. perforatum had anti-inflammatory properties and significantly decreased all the inflammatory parameters." (PMID 33344682, 2020). "There are significant increases in the salivary levels of NLRP3, apoptosis-associated speck-like protein containing a caspase recruitment domain (ASC), and IL-1β in chronic periodontitis and aggressive periodontitis." (PMID 31900383, 2020).